FGF21 (fibroblast growth factor 21)
Diseases named in the same sentence as FGF21 in open-access papers (continued):
Sharing a sentence is not in itself a finding about the gene and the disease.
diabetes (continued). "Notably, our study population was newly diagnosed with type-2 diabetes without the intervention of drugs and other therapeutic factors, which makes the association analysis of FGF-21 and diabetes more definite." (PMID 37658393, 2023). "The FGF-21 level was independently associated with aortic stiffness (odds ratio (OR): 1.008; 95% CI: 1.003–1.012; P=0.001) after adjusting for diabetes mellitus, age, hypertension, C-reactive protein, and body weight in multivariable logistic regression analysis." (PMID 35186330, 2022). "Several studies have shown an association between FGF21 and diabetes." (PMID 35677107, 2022). "Since endothelial dysfunction is one of the pathophysiological pathways of ED, it is hypothesized that FGF21 is associated with ED in men with diabetes." (PMID 36213282, 2022). "Accumulating evidence indicates that elevated FGF21 concentrations are associated with a higher incidence of diabetes, chronic kidney disease, hypertension, and cardiovascular diseases, including coronary artery disease, heart failure, atrial fibrillation and AMI." (PMID 34703671, 2021). "Furthermore, net reclassification improvement and integrated discrimination improvement analyses showed that FGF21/adiponectin ratio provided a better performance in diabetes risk prediction than the use of FGF21 or adiponectin alone." (PMID 34321008, 2021). "Notably, we found that FGF21/adiponectin ratio provided an improvement in diabetes risk prediction, compared with the use of FGF21 (NRI = 23.5%, p = 0.002; IDI = 0.3%, p = 0.014) or adiponectin (NRI = 18.3%, p = 0.016; IDI = 0.3%, p = 0.161) alone." (PMID 34321008, 2021). "Fibroblast growth factor 21 (FGF21) is closely linked with metabolic disorders including diabetes." (PMID 31205953, 2019). "In the total study population, higher levels of serum FGF-21 were significantly associated with increased diabetes risk after adjustment for age, sex, lifestyle factors, fasting status and BMI; the OR (95% CI) comparing the highest versus lowest quartile was 2.70 (1.33–5.50; P-trend = 0.015)." (PMID 29021814, 2017). "In addition, we have observed sex-interaction in the association between FGF-21 and diabetes in this Chinese population." (PMID 29021814, 2017). "In addition, further adjustment for menopausal status in women had little impact on the association between FGF-21 and diabetes (OR per log FGF-21: 1.50; 95% CI 1.00–2.25)." (PMID 29021814, 2017). "Some prospective studies have shown a positive association between FGF-21 and diabetes risk." (PMID 29021814, 2017). "A 5.4-year prospective cohort study among 1292 Chinese (73 diabetes cases) in Hong Kong reported an OR of 1.79 (95% CI 1.22–2.64) for the risk of diabetes with per 1 unit increment in log FGF-21 levels, after adjusting for fasting glucose, insulin, TG, HDL-C and hs-CRP." (PMID 29021814, 2017). "Additionally, we assessed the incremental value of FGF-21 in diabetes risk prediction over established risk factors in this population." (PMID 29021814, 2017). "In this nested case-control study within the Singapore Chinese Health Study, we studied the association between FGF-21 and risk of type 2 diabetes with adjustment of established diabetes risk factors including two liver enzymes alanine transaminase (ALT) and gamma-glutamyltransferase (GGT)." (PMID 29021814, 2017). "Here we investigate the effects of exogenous administration of FGF21 to obese and insulin-resistant NZO mice, and evaluate the potential of the diabetes-susceptible NZO mouse as an animal model to study endogenous FGF21 actions in regard to the prevention of diabetes in the future." (PMID 28770320, 2017). "Therefore, we prospectively evaluated the sex-specific association between FGF-21 and diabetes in a Chinese population." (PMID 29021814, 2017). "Diabetes-induced pathogenic effects in the heart are enhanced in FGF21 knockout mice." (PMID 27803896, 2016).
diabetes (continued). "FGF21 knockout mice are more susceptible to diabetes-induced cardiac apoptosis, and this may be prevented by the administration of FGF21." (PMID 27803896, 2016). "Recently, we reported that cardiac FGF21 mRNA expression was positively associated with the development of diabetes in the type 1 diabetic mice, suggesting that the increased cardiac FGF21 expression may be beneficial to the heart in this regard." (PMID 27247947, 2016). "Furthermore, stepwise logistic regression analysis revealed that plasma FGF21 was independently associated with diabetes." (PMID 21525989, 2011). "Elevated FGF21 concentrations are also associated with an increased risk of glycemic deterioration and may serve as an alternative to the oral glucose tolerance test for early diabetes prediction." (PMID 40426925, 2025). "FGF-21 could be used as a biomarker in diabetes risk assessment." (PMID 37658393, 2023). "Furthermore, FGF-21 attenuates atherosclerosis and inflammation in diet-induced obese ApoE-deficient rodents and protects against cardiomyopathy and kidney disease in people with diabetes." (PMID 37288111, 2023). "In addition, FGF-21 improved diabetes risk reclassification among women." (PMID 29021814, 2017). "Furthermore, two studies have examined whether FGF-21 added substantial value in predicting diabetes risk, and the results were inconsistent." (PMID 29021814, 2017). "Therefore, whether estrogen played an important role in the association between FGF-21 and diabetes risk remains to be explored." (PMID 29021814, 2017). "Previous studies have identified significant correlations between FGF-21 levels and metabolic syndrome (MetS), as well as related disorders such as diabetes mellitus, the progression of kidney disease in diabetes, and coronary artery disease." (PMID 40559404, 2025). "On the other hand, rBMAds boosters include a high-fat diet, caloric restriction (CR), treatments with thiazolidinediones and glucocorticoids, fibroblast growth factor 21 (FGF21), insulin-dependent diabetes mellitus (type I diabetes), irradiation, and aging." (PMID 40497990, 2025). "FGF21 is a growth factor that has been reported to protect against various insults, such as cardiac hypertrophy, sepsis toxicity, diabetes-induced cardiac cell apoptosis, high glucose-induced endothelial cell damage, and glutamate-induced neuron death 17-21." (PMID 39744501, 2025). "At the same time, β-Klotho-related FGF21 analogue drugs have entered the clinical trial stage, providing new possibilities for the treatment of diabetes." (PMID 41438297, 2025). "Together, these findings support the concept that appropriate protein intake can attenuate FGF21-mediated stress responses, thereby contributing to muscle preservation in older adults with diabetes." (PMID 41228530, 2025). "Current research has expanded the therapeutic applications of FGF21 beyond metabolic diseases to include the treatment of diabetes-induced skin lesions and the promotion of wound healing, revealing novel pharmacological properties." (PMID 40231082, 2025). "Elevated FGF-21 levels have been recognized as a potential therapeutic target in metabolic disease, particularly in individuals with impaired glucose tolerance and diabetes." (PMID 40943671, 2025). "In alignment with the non-diabetes network, BasalISR emerged as a putative upstream driver influencing liver fat accumulation with the FGF21 (fibroblast growth factor 21) protein as a downstream target of liver fat." (PMID 40502600, 2025). "In the OVE26 diabetic mouse model, the administration of RGFP-966 (an HDAC3 inhibitor) facilitated the synthesis of Fibroblast Growth Factor 21 (FGF21) in the liver and decreased the incidence of diabetes-related aortic lesions." (PMID 40006729, 2025). "In our 5.4-year prospective study, elevated FGF21 level was found in participants with prediabetes and diabetes at baseline." (PMID 40356318, 2025).
diabetes (continued). "In our research, we have, for the first time, identified a positive association between serum FGF-21 levels and IMT in obese individuals experiencing early carbohydrate metabolism disorders, specifically prediabetes and newly diagnosed diabetes." (PMID 40559404, 2025). "A study has reported elevated serum FGF-21 levels in response to diabetes-induced early-stage atherosclerosis." (PMID 39544568, 2024). "A recent study from Saudi Arabia concluded that FGF-21 can also be used as a marker to predict non-alcoholic fatty liver disease in people with diabetes mellitus type 2 due to its high sensitivity and specificity compared to the other markers." (PMID 38333506, 2024). "Within the framework of this study, the primary objective was to elucidate the impacts of FGF21 on neurodegenerative processes in the context of aging and diabetes in murine models." (PMID 39459367, 2024). "Our study reveals a new mechanism by which diabetes accelerates vascular senescence and identifies the pharmacological effect of FGF21 in mitigating diabetes-induced vascular senescence, providing new evidence for its potential clinical application." (PMID 38733164, 2024). "To investigate the effect of FGF21 on NLRP3 inflammasome activation induced by diabetes, we assessed the extent of NLRP3 inflammasome activation in the aortas of diabetic mice and smooth muscle cells." (PMID 38733164, 2024). "The low intrinsic stability and limited blood retention are major issues for the potential use of FGF21 as therapeutics in metabolic diseases such as diabetes." (PMID 38379823, 2024). "After adjustment for age, gender, hypertension, diabetes, hyperlipemia, smoking, and alcohol use, the incidence of ischemic stroke was positively correlated with ln-transformed FGF21 levels (OR [95%CI] = 1.944 [1.029,3.672], P = 0.04)." (PMID 38789571, 2024). "By modulating oxidative stress, lipid metabolism FGF21 has therapeutic properties for a wide range of human ailments, including alopecia, diabetes mellitus, and renal disease." (PMID 38333506, 2024). "In this sense, a study showed that diabetic individuals diagnosed with CVD had high levels of FGF21, suggesting an important role for FGF21 in atherosclerosis accelerated by diabetes." (PMID 39519454, 2024). "The findings of the present study revealed the novel pharmacological effects of FGF21 in protecting VSMCs, specifically by alleviating the senescence of the smooth muscle layer induced by diabetes." (PMID 38733164, 2024). "In diabetes, FGF21 is commonly considered to be a protective factor due to its insulin-sensitizing and anti-inflammatory effects." (PMID 38540101, 2024). "In a mouse model of lipotoxicity and diabetes, FGF21 partially prevented renal injury induced by free fatty acids and diabetes by reducing renal lipid accumulation and inhibiting inflammation, oxidative stress (OS), and fibrosis." (PMID 38312833, 2024). "This conclusion provides new evidence for the role of FGF21 in counteracting the increase in oxidative stress induced by diabetes." (PMID 38733164, 2024). "We meticulously balanced the proportion of diabetic patients between the two groups to mitigate the potential confounding effect of diabetes on serum FGF21 levels in RAO patients." (PMID 38789571, 2024). "The vascular protective effect of FGF21 has gradually gained increasing attention, but its role in diabetes-induced vascular senescence needs further investigation." (PMID 38733164, 2024). "Diabetes was associated with increased angiogenesis through an increase in VEGF, TGF-β, FGF-21, TNF-α and NO levels and a decrease in FLK-1 and sFLT-1 levels." (PMID 38584657, 2024). "Mechanistic studies have reported that inhibition of Hdac3 is implicated in the regulation of gluconeogenesis, oxidative metabolism and hepatic FGF21 expression in diabetes." (PMID 39580381, 2024).
diabetes (continued). "The diabetes-resistant phenotype following hepatic and intestinal complex I inhibition is attributed to FGF21- and GDF15-dependent fat hunger signaling, which remodels adipose tissue into a glucose-metabolizing organ." (PMID 38267672, 2024). "As vitamin D has an active role in the pathogenesis of diabetes and its complications, in the present study, we assessed the link of vitamin D levels with adiponectin, FGF-21, and inflammatory and oxidative stress markers in newly diagnosed T2DM." (PMID 39544568, 2024). "Independently, the FGF21/adiponectin ratio predicted the emergence of pre-diabetes and diabetes in a prospective Shanghai Nicheng cohort study." (PMID 37214383, 2023). "This is consistent with numerous reports in which FGF21 levels were also observed to be higher in type 2 diabetic patients than in subjects free from diabetes." (PMID 37869250, 2023). "Accordingly, this study aimed to determine the stability of the association between FGF-21 and the risk of newly diagnosed T2DM in different populations and evaluated the efficiency of FGF-21 in diabetes risk assessment." (PMID 37658393, 2023). "The liver is a key organ of glucose regulation, and FGF21 secreted by the liver has been confirmed to be closely related to the occurrence and development of diabetes." (PMID 37576954, 2023). "At the same time, our results also provide evidence to investigate the mechanism of FGF-21 and its relationship with the development of type-2 diabetes mellitus." (PMID 37658393, 2023). "Protein-based diabetes drugs, such as fibroblast growth factor-21 (FGF-21), have a longer-lasting glycemic modulating effect with high biosafety." (PMID 37514488, 2023). "This study investigated the relationship between fibroblast growth factor 21 (FGF-21) and newly diagnosed type-2 diabetes mellitus (T2DM)." (PMID 37658393, 2023). "This study aims to evaluate the relationship between serum FGF21 levels and body shape parameters in patients with hypertension (HP) and type 2 diabetes mellitus (T2DM)." (PMID 37424900, 2023). "The prevalence of abdominal obesity is high, and an increased serum level of FGF21 was observed in HP individuals with diabetes." (PMID 37424900, 2023). "Another study illustrated that recombinant FGF21 activated CaMKK2/AMPKα signaling, enhancing eNOS phosphorylation and reducing oxidative stress responses to ameliorate diabetes-induced aortic endothelial disorders." (PMID 37416922, 2023). "According to the results of this study, AME has beneficial effects on protecting against diabetes-related aberrant peripheral energy metabolism through activation of the PGC1α/SIRT1-dependent mechanism by FGF21." (PMID 37299522, 2023). "As a peroxisome-proliferator-activated receptor agonist, the protective effect of Fenofibrate in the diabetes-induced cardiac remodeling was depended on FGF21- Sirtuin-1 (SIRT1) activated autophagy." (PMID 37416922, 2023). "FGF21 levels in circulation, cord blood, and placenta were elevated in pregnant women with diabetes mellitus, and positively correlated with human BMI." (PMID 37424900, 2023). "The mechanism of elevated FGF21 under various stress conditions including diabetes, CAS, and HP still under study." (PMID 38057786, 2023). "There were elevated serum levels of FGF21 in patients with diabetes compared with control individuals." (PMID 37576954, 2023). "Apart from being a metabolic regulator, Fgf-21 was also found to play roles in promoting spermatogenesis, protecting germ cells from diabetes-induced apoptosis, and increasing sperm motility." (PMID 38075064, 2023). "There was a strongly positive significant correlation of serum FGF21 with BMI, left cIMT, and right cIMT in the total diabetes sample." (PMID 38057786, 2023). "FGF21 is also expressed in the pancreas where it improves β-cell function and survival in rodent models of diabetes through the activation of the extracellular mitogen activated protein kinase 1 and 2 (ERK1/2) and Akt signalling pathways." (PMID 36028609, 2023).
diabetes (continued). "In present study, we evaluated the changes of serum FGF21 level in patients with T2DM and diabetes-associated vascular complications including CAS and HP, and healty control." (PMID 38057786, 2023). "Nomograms and ROC curves were used to explore the clinical utility of FGF-21 in the diabetes assessment model." (PMID 37658393, 2023). "Baseline FGF21 is elevated in VDs during diabetes, changes of serum FGF21 levels were appropriately matched to metabolic stress." (PMID 38057786, 2023). "Ranking these candidates based on CMAP score revealed a number of well-known potentiators of insulin sensitivity including the antioxidant resveratrol, the diabetes medication metformin, and the growth factor FGF21." (PMID 37494090, 2023). "Fibroblast growth factor 21 (FGF21) has been identified as a critical regulator playing a therapeutic role in diabetes and its complications." (PMID 37424900, 2023). "Although FGF21 has shown a protective effect in the treatment of diabetes, the effect of FGF21 and its analogs on lowering blood glucose levels is still not obvious in current clinical trials." (PMID 37576954, 2023). "FGF21 was first identified in 2005 as a novel metabolic regulator with therapeutic effects in diabetes treatments." (PMID 37462619, 2023). "For example, FGF21 blocks the nuclear translocation of NF-κB in adipocytes and AT under conditions of insulin resistance, ameliorating inflammation in diabetes and simultaneously improving glucose metabolism." (PMID 35909571, 2022). "High serum FGF21 levels have been shown in obese patients with type 2 diabetes mellitus and metabolic syndrome." (PMID 35510201, 2022). "In a recent study, both endogenous and exogenous FGF21 prevented cardiac apoptosis in type 1 diabetes mellitus (T1DM) mice by inhibiting lipotoxicity." (PMID 35159376, 2022). "Serum FGF21 levels were found to be lower in mice with streptozotocin-induced type 1 diabetes and in patients with type 1 diabetes mellitus (T1DM)." (PMID 35192641, 2022). "Fibroblast growth factor 21 increased in population with type 2 diabetes mellitus (T2DM), while serum total testosterone often decreased in men with T2DM." (PMID 35909513, 2022). "In a streptozotocin-induced diabetes model, FGF21 was found to play a role in enhancing islet transplantation survival." (PMID 36618930, 2022). "FGF21 analogs are reported to adjust systemic metabolism in obese and diabetes in clinical trials and pre-clinical studies." (PMID 35983184, 2022). "FGF21 can prevent both hyperlipidemia and diabetes-induced renal damage, which was partially by reducing renal lipid accumulation and decreasing inflammation, oxidative stress and fibrosis." (PMID 35369322, 2022). "Exogenous FGF21 alleviates diabetes-induced myocardial fibrosis by promoting Akt phosphorylation and inhibiting the expression of downstream proinflammatory factors." (PMID 35677107, 2022). "Serum levels of FGF21 are elevated in obese humans, and this protein has been suggested as a potential biomarker of Metabolic syndrome (Mets) and Type 2 Diabetes Mellitus (T2DM)." (PMID 35740758, 2022). "Due to the function of lowering plasma glucose and lipid levels, FGF21 has been suggested as a potential therapeutic agent for diabetes, obesity, and dyslipidemia." (PMID 35677107, 2022). "A recent study of FGF21 KO diabetic mice indicates that FGF21 deletion exacerbates diabetes-induced cardiac fibrosis remodeling." (PMID 35677107, 2022). "A study identified that FGF21 levels were increased at the early stage of hepatic stress in a genetic model mouse presenting diabetes-steatohepatitis; however, the reduction in FGF21 levels was reported when HCC was well-developed." (PMID 36457562, 2022).